JAK2 (Janus kinase 2)
Diseases named in the same sentence as JAK2 in open-access papers (continued):
Sharing a sentence is not in itself a finding about the gene and the disease.
Cerebral ischemia (continued). "In our rat model of permanent cerebral ischemia, pretreatment with the Jak2 inhibitor AG490 protected brains from poststroke apoptosis and injury, although the putative protective or deleterious roles of the Jak2 signaling pathway in cerebral ischemia have yet to be determined." (PMID 34943061, 2021). "Besides this, the inhibition of the Jak2/Stat3 pathway that can be activated with excess IL-6 during the acute phase of cerebral ischemia confers neuroprotection in ischemic stroke." (PMID 34943061, 2021). "There are contrary functional options about JAK2/STAT3 activation in cerebral ischemia." (PMID 31827699, 2019). "In addition, double-immunofluorescence staining also demonstrated that astrocytic p-STAT3 and p-JAK2 levels were markedly increased after cerebral ischemia but were diminished by EGB treatment." (PMID 29867513, 2018). "Furthermore, gastrodin may directly bind to JAK2 and reduce the production of inflammatory cytokines after cerebral ischemia by inhibiting JAK2/STAT3 signaling." (PMID 40756985, 2025). "The JAK2/STAT3 signalling pathway is critically involved in regulating the formation of various tumours and cerebral ischemia and Alzheimer's Disease (AD) treatment." (PMID 39392081, 2024). "According to studies, the post-ischemic inflammatory response is mediated by the JAK2/STAT3 signaling pathway, which can be activated after cerebral ischemia." (PMID 37886007, 2023). "At present, experiments have demonstrated that curcumin can improve neuronal survival rate by activating JAK2/STAT3 signals, as well as reduce cerebral ischemia-reperfusion injury." (PMID 36598916, 2023). "A member of its family, the JAK2/STAT3 signal pathway, is involved in neuronal death and nervous reorganization in ischemic encephalopathy." (PMID 35468096, 2022). "Middle cerebral artery occlusion (MCAO) wasperformed to establish a cerebral ischemia/reperfusion (I/R) model.Specific-pathogen-free male Sprague-Dawley rats were randomly divided into Sham,I/R, DEX, DEX+IL-6, and AG490 (a selective inhibitor of JAK2) groups." (PMID 35858000, 2022). "We used a Jak2 inhibitor, AG490, to explore its effects on inflammation in the cerebral cortical, hepatic, and skeletal muscle tissues, and in the changes of the insulin signaling in a rat model of acute cerebral ischemia." (PMID 34943061, 2021). "By inhibiting JAK2/STAT3 signaling pathway, curcumin reduces the expression of HMGB1 in brain tissue after cerebral ischemia and reduces the release of TNF‐α and other inflammatory factors after cerebral ischemia, which significantly reduce the inflammatory response after cerebral ischemia." (PMID 38156383, 2023).
cervical carcinoma (34 papers, 2010 to 2025). A carcinoma arising from either the exocervical squamous epithelium or the endocervical glandular epithelium. "Here, we demonstrate that JAK2 is aberrantly phosphorylated in cervical cancer cells and that inhibition of JAK2 results in the loss of STAT3 phosphorylation." (PMID 31817106, 2019). "Previous studies have shown that selenadiazole can suppress tumor growth in cervical cancer cells by elevating intracellular ROS levels and triggering mitochondrial apoptosis through modulation of the JAK2/STAT3 signaling pathway." (PMID 41516206, 2025). "Among these, SL10 (12.7 nM) and SL35 (21.7 nM) demonstrated potent JAK2 inhibition and exhibited selective cytotoxicity toward HeLa cervical cancer cells, outperforming ruxolitinib." (PMID 41516206, 2025). "Collectively, these findings provide mechanistic insights into structure–activity relationships and highlight sesquiterpene lactone scaffolds as promising candidates for the development of targeted JAK2 inhibitors in cervical cancer therapy." (PMID 41516206, 2025). "And anlotinib not only inhibited the secretion of pro-cancer cytokines induced by CAFs, but also inhibited the phosphorylation of Jak2 and Stat3 in cervical cancer cells induced by CAFs." (PMID 39193386, 2024). "CAF-CM increased the phosphorylation levels of Jak-2 and Stat3 in cervical cancer cell lines, however, treatment with anlotinib attenuated this promotion." (PMID 39193386, 2024). "Quercetin nanoparticles inhibit the development of cervical cancer by inducing apoptosis and autophagy and decreasing cervical cancer cell proliferation by blocking Janus kinase 2 (JAK2) activation." (PMID 39844873, 2024). "MUC16 promoted growth and invasion of cervical cancer cells via JAK2/STAT3 phosphorylation-mediated COX-2 expression." (PMID 34150633, 2021). "Having shown both STAT3 and STAT5 are substrates for JAK2 in HPV+ cervical cancer cells, it was important to understand if the phosphorylation and activation of these proteins correlated during disease progression." (PMID 31817106, 2019). "Inhibition of either JAK2 or STAT5 results in impaired proliferation in HPV+ cervical cancer cells and the induction of apoptosis." (PMID 31817106, 2019). "In conclusion, we have demonstrated for the first time that the targeting of JAK2 using the clinically available inhibitior ruxolitinib inhibits proliferation in HPV+ cervical cancers cells and induces apoptosis." (PMID 31817106, 2019). "We therefore investigated the impact of JAK2 inhibition on the cell cycle in HPV+ cervical cancer cells." (PMID 31817106, 2019). "This suggests that the effect of JAK2 inhibition on cell proliferation is specific to HPV+ cervical cancer cells, corresponding with the higher levels of JAK2 phosphorylation in these cells." (PMID 31817106, 2019). "Together, these data demonstrate the importance of JAK2 mediated signalling in driving the proliferation of HPV+ cervical cancer cells by using highly specific, clinically validated small molecule inhibitors." (PMID 31817106, 2019). "To confirm if JAK2 phosphorylation remained elevated in cervical cancer, we performed western blot on lysates from a panel of six cervical cancer cell lines." (PMID 31817106, 2019). "The JAK2/STAT3 pathway has been reported to play a crucial role in regulating the progression of cervical cancer." (PMID 26219895, 2016). "Furthermore, they found that JAK2 phosphorylation correlates with both STAT3 and STAT5 phosphorylation, highlighting JAK2/STAT3 and JAK2/STAT5 are functional in cervical cancer cell." (PMID 41516206, 2025). "Additionally, miR-204-5p, located in exosomes released from HPV16 E6-positive cervical cancer cells, was found to directly suppress JAK2 in the recipient macrophages, resulting in polarization toward the anti-inflammatory M2 phenotype." (PMID 41154440, 2025). "In this study, we found that IL-6 and IL-8 could promote the phosphorylation levels of Jak-2 and Stat3 proteins in cervical cancer cells." (PMID 39193386, 2024).
cervical carcinoma (continued). "In addition, we also demonstrated that recombinant IL-6 and IL-8 proteins can promote the phosphorylation of Jak-2 and Stat3 in cervical cancer cell lines, and anlotinib can neutralize this promoting effect." (PMID 39193386, 2024). "Furthermore, it has been reported that MUC16 promotes proliferation and invasion via activation of the JAK2/STAT3 pathway in cervical cancer." (PMID 36199046, 2022). "We then assessed if JAK2 was required for the phosphorylation of STAT5 in cervical cancer cells." (PMID 31817106, 2019). "Together, these results suggest that JAK2 inhibitors may potentially be utilised as combination therapies with currently approved cervical cancer chemotherapeutic, such as cisplatin." (PMID 31817106, 2019). "We therefore rationalised that inhibition of STAT3 using the clinically approved JAK2 inhibitor ruxolitinib may synergise with cisplatin in inducing cell death in HPV+ cervical cancer cells." (PMID 31817106, 2019). "We therefore assessed if the inhibition of JAK2 using ruxolitinib could synergise with cisplatin in HPV+ cervical cancer." (PMID 31817106, 2019). "Therefore, further studies are required in order to investigate the potential downstream targets of JAK2 that may be involved in cell cycle progression in cervical cancer cells." (PMID 31817106, 2019). "Furthermore, it was reported that the JAK2/STAT3 pathway regulates cervical cancer progression." (PMID 26219895, 2016). "Janus kinase 2 (JAK2) is a key mediator of oncogenic signaling and a promising therapeutic target in cervical cancer." (PMID 41516206, 2025). "In the microenvironment of cervical cancer, expression levels of B7-H3 and B7-H4 positively correlated with the expression levels of IL-10 and TGF-β1, suggesting correlation with the p-JAK2/STAT3 pathway." (PMID 38850312, 2024). "Previous data from our group had shown that IL6R, JAK1/JAK2, and STAT3/STAT5b were dysregulated in locally advanced cervical cancer." (PMID 38891028, 2024). "In cervical cancer cells, propofol is able to induce cisplatin-mediated cellular apoptosis through repression of the EGFR/JAK2/STAT3 pathway." (PMID 35517791, 2022). "The activation of STAT3 determines the sensitivity of cervical cancer cells to TRAIL-induced apoptosis and can be abrogated by inhibiting the Janus kinase 2 (JAK2), which phosphorylates STAT3." (PMID 36145459, 2022). "MiR-126 can inhibit the expression of MMP2 by targeting ZEB1, which inhibits the protein expression of p-JAK2 and p-STAT3 and inactivates the JAK2/STAT3 signaling pathway, which inhibits the proliferation, migration and invasion of cervical cancer cells." (PMID 33967611, 2021). "When inhibiting JAK2 by using the clinically available inhibitor ruxolitinib, this leads to the inhibition of proliferation and induction of apoptosis in HPV positive cervical cancer cells." (PMID 33926008, 2021). "In cervical cancer, propofol heightens the cisplatin-triggered cancer cell apoptosis via blocking EGFR/JAK2/STAT3 axis." (PMID 34775376, 2021). "Finally, we demonstrate that the clinically available inhibitor Ruxolitinib synergises with cisplatin in the induction of apoptosis in cervical cancer cells, suggesting that pharmalogical targeting of JAK2 may have therapeutic benefit in HPV-driven malignancies." (PMID 31817106, 2019). "JAK2 inhibition also resulted in an arrest of the cell cycle and the induction of apoptosis in HPV+ cervical cancer cells." (PMID 31817106, 2019). "The data in this study, and our previous work, demonstrate that JAK2 can activate both STAT3 and STAT5 signalling in HPV+ cervical cancer cells, suggesting that both pathways contribute to the tumourigenesis of these cancers." (PMID 31817106, 2019). "Here, we demonstrate that inhibiting JAK2 reduces cell proliferation and induces apoptosis in HPV transformed cervical cancer cells." (PMID 31817106, 2019).
cervical carcinoma (continued). "The ovarian and cervical cancer cell line selective inhibitors included TG-89 (IC50 = 11.2 ± 7.28 μM; SI >100), a JAK2 inhibitor, and CCT137690 (IC50 = 20.0 ± 7.02 μM; SI >100), an Aurora kinase inhibitor." (PMID 30576957, 2019). "One promising molecular target for cervical cancer therapy is Janus kinase 2 (JAK2), a member of the non-receptor protein tyrosine kinase family." (PMID 41516206, 2025). "Similarly, upon downregulation of LINC00518 expression, the protein levels of p-JAK2 and p-STAT3 decreased in HeLa cervical cancer cells as well." (PMID 39108268, 2024). "In cervical cancer cells, previous study showed that propofol could enhance cisplatin-induced apoptosis via EGFR/JAK2/STAT3 pathway." (PMID 28542400, 2017). "In addition, exosomes derived from cervical cancer enriched in miR-1468-5p were taken up by lymphatic endothelial cells (LECs), where they suppressed HMBOX1 and the downstream protein SOCS1, activating the JAK2/STAT3 pathway." (PMID 41154440, 2025). "EPOR is expressed in cervical cancer, and the binding of erythropoietin (Epo) to its receptor induced cell proliferation; such cell response was related to the activation of JAK2, JAK3, STAT3, and STAT5, but not JAK1 and STAT1 in cervical cancer." (PMID 37372319, 2023). "We observed an increase in JAK2 phosphorylation in lysates from both HPV16 positive (HPV16+; SiHa and CaSKi) and HPV18 positive (HPV18+; SW756 and HeLa) cervical cancer cell lines when compared to HPV negative (HPV−; C33A and DoTc2) cervical cancer cells." (PMID 31817106, 2019). "Previous studies have shown that treatment of SiHa HPV16-positive cervical cancer cells with AG490, a non-specific JAK2 inhibitor, prevented STAT3 Y705 phosphorylation, however, such studies have not been performed in primary keratinocytes." (PMID 29630659, 2018). "Inhibition of JAK2 using the non-selective compound AG490 has demonstrated that JAK2 activity is required for STAT3 phosphorylation and viral oncogene expression in HPV+ cervical cancer cells." (PMID 31817106, 2019).
non-small cell lung carcinoma (34 papers, 2012 to 2025). A group of at least three distinct histological types of lung cancer, including non-small cell squamous cell carcinoma, adenocarcinoma, and large cell carcinoma. "ALKBH5 promotes non-small cell lung cancer progression by regulating cancer and tumor-associated macrophage behavior through the JAK2/p-STAT3 pathway and the expression of CCL2 and CXCL10, respectively." (PMID 38872221, 2024). "The inhibition of the IL6/IL8 - JAK2 signaling can eliminate BRD4 phosphorylation and restore the sensitivity of tumors to BET inhibitors.In KRAS - mutated tumors, including non - small - cell lung cancer (NSCLC), an up - regulation of BCL6 has been observed." (PMID 39838405, 2025). "It is noteworthy that the latest report has revealed that FXR promotes non-small-cell lung cancer metastasis by activating the Jak2/STAT3 signaling pathway through the transactivation of the IL6ST and IL6 genes." (PMID 39940889, 2025). "JAK2 was identified as a target of ALKBH5-mediated m6A modification, which activates the JAK2/p-STAT3 pathway to promote non-small cell lung cancer progression." (PMID 38872221, 2024). "For instance, BAs activate the FXR receptor, thereby promoting the metastasis of non-small cell lung cancer (NSCLC) by mediating the JAK2/STAT3 signaling pathway through the transactivation of IL-6ST and IL-6 genes." (PMID 39769418, 2024). "Over the last years however, CXCL12-induced JAK2/STAT3 signaling in human non-small-cell lung cancer cells and JAK2/STAT3 and JAK3/STAT6 signaling in a human proximal tubular cell line was demonstrated." (PMID 36725964, 2023). "Recently, the JAK2 inhibitor (SAR302503) role in suppressing STAT1 activation in radioresistant non-small cell lung cancer (NSCLC) cell lines has been recorded." (PMID 33922087, 2021). "The JAK2/STAT3 signaling pathway has been reported to be closely associated with the development and metastasis of non-small-cell lung cancer." (PMID 33195699, 2020). "A different study suggested that combination of JAK2 inhibitors with immune checkpoint inhibition is effective for the treatment of non-small-cell lung cancer." (PMID 33029256, 2020). "recent work showed that the membrane bile acid receptor, TGR5, not only induces but also drives the growth and migration of non-small cell lung cancer cells by activating JAK2/STAT3 signaling." (PMID 31492006, 2019). "Furthermore the efficacy of the JAK2 inhibitor Ruxolitinib is currently being investigated in combination with cisplatin in clinical trials in non-small cell lung carcinoma (NSCLC)." (PMID 28418910, 2017). "Furthermore, the upregulation of VEGF mediated by the activation of JAK2/STAT3 signaling pathway has been demonstrated in non-small-cell lung cancer and other tumor cells, indicating that a similar correlation may also exist in mtLE subpopulation." (PMID 36620436, 2022). "In non-small-cell lung cancer (NSCLC), ALKBH5 mediated m6A modification of JAK2 mRNA, activated the JAK2/p-STAT3/CCL2/CXCL10 axis, leading to the recruitment of PD-L1 + TAMs and promoting M2 macrophage polarization." (PMID 39987091, 2025). "Our data suggest that the aberrant expression of EML4-ALK leads to JAK2-STAT signaling pathway activation, which is essential for the development of non-small cell lung cancer." (PMID 34090412, 2021). "In conclusion, our data suggest that aberrant expression of EML4-ALK leads to the activation of the JAK2-STAT signaling pathway, which is essential for the development of non-small cell lung cancer." (PMID 34090412, 2021). "The l1 penalty function has previously been applied to an EPO induced JAK2/STAT5 signalling pathway to find cell-type specific behaviour between healthy CFU-E cells and non-small cell lung cancer cells of type H838." (PMID 31311516, 2019).
non-small cell lung carcinoma (continued). "Paradoxically, we find that YSY01A abrogates constitutive activation of STAT3 via proteasome-independent degradation of gp130 and JAK2, but not transcriptional regulation, in human A549 non-small cell lung cancer cells." (PMID 28883791, 2017). "Additionally, AHR drives non-small cell lung cancer tumorigenesis when the AHR protein is stabilized after deubiquitination by ubiquitin carboxy-terminal hydrolase isozyme L3, and this AHR action of cancer tumorigenesis may involve Jak2/STAT3 signaling." (PMID 37894798, 2023).